TMIGD3 (transmembrane and immunoglobulin domain containing 3)
Description:
[Isoform 1]: Plays a suppressive role in osteosarcoma malignancy by inhibiting NF-kappa-B activity.
Synonyms: AD026
Tractability: Small molecule: a high-quality ligand is known; it belongs to a druggable protein family. Antibody: its Gene Ontology location is reachable by antibodies, with high confidence; UniProt predicts a signal peptide or a membrane-spanning region. PROTAC: a small molecule that binds it is known.
Gene: Protein-coding gene on chromosome 1 (111,483,348 to 111,563,962, reverse strand). Ensembl gene ENSG00000121933.
Subcellular location: Membrane
Gene Ontology:
Molecular function: transmembrane signaling receptor activity
Biological process: negative regulation of cell migration; negative regulation of cell population proliferation; activation of adenylate cyclase activity; immune response-activating signaling pathway; inflammatory response; regulation of heart contraction; response to wounding; signal transduction
Cellular component: membrane; plasma membrane
Genetic constraint (gnomAD): Loss-of-function variants: 16 observed, 25.95 expected, observed/expected ratio (o/e) 0.62, 90% interval 0.42 to 0.94. The upper end of that interval is the gene's LOEUF score, 0.94, which puts it in group 3 of 6, group 1 being the genes least tolerant of losing a copy. Missense variants: 411 observed, 449.75 expected, observed/expected ratio (o/e) 0.91, 90% interval 0.84 to 0.99. Synonymous variants: 150 observed, 168.44 expected, observed/expected ratio (o/e) 0.89, 90% interval 0.78 to 1.02.
Homologues: Orthologues: chimpanzee TMIGD3 (99% identical), macaque TMIGD3 (95% identical), pig ADORA3 (82% identical), rat Tmigd3 (43% identical), mouse Tmigd3 (39% identical). Paralogues in human: CD300LG (15% identical), CD300E (12% identical), CD300H (12% identical), CD300A (12% identical), CD300LB (12% identical), PIGR (12% identical), FCAMR (11% identical), CD300C (11% identical), FCMR (11% identical), TREML1 (11% identical), CD300LD (10% identical), TREM2 (9% identical), and 1 more.
Diseases named in the same sentence as TMIGD3 in open-access papers:
TMIGD3 is named in the same sentence as 9 diseases in open-access papers, as found by Europe PMC text mining. Sharing a sentence is not in itself a finding about the gene and the disease. The quoted sentences say what the papers report.
osteosarcoma (3 papers, 2016 to 2023). A usually aggressive malignant bone-forming mesenchymal neoplasm, predominantly affecting adolescents and young adults. "A recent study revealed that in osteosarcoma cells, TMIGD3 suppresses aggressiveness primarily by inhibiting NF-κB activity." (PMID 37109675, 2023). "TMIGD3 represents the third member, which is reported to act as a tumor suppressor in osteosarcoma." (PMID 29515762, 2018).
asthma (1 paper, 2023). "GSEA analysis indicated that the TMIGD3 was primarily enriched in asthma, allograft rejection, primary immunodeficiency and graft versus host disease." (PMID 37109675, 2023).
esophageal cancer (1 paper, 2023). A primary or metastatic malignant neoplasm involving the esophagus. "Among patients with esophageal cancer, TMIGD3 played a key role in the immune/stromal scores, and disease stage pathological type was associated with a shorter overall survival rate." (PMID 37109675, 2023).
tumor (3 papers, 2016 to 2023). "We next evaluated the correlation analysis between TMIGD3 and tumor mutational burden (TMB), microsatellite instability (MSI) and mRNAsi score." (PMID 37109675, 2023). "The single-cell expression pattern, biological investigation and tumor microenvironment of TMIGD3 exerting in PC were also explored, making it an underlying biomarker for PC." (PMID 37109675, 2023). "For the tumor microenvironment analysis, we discovered that TMIGD3 was positively correlated with monocyte, M2 macrophages and endothelial cell." (PMID 37109675, 2023). "Tumor microenvironment analysis indicated that TMIGD3 was positively correlated with monocyte_MCPCOUNTER, NK cell_MCPCOUNTER, macrophages M2_CIBERSORT, macrophage_EPIC, neutrophil_TIMER and endothelial cell_MCPCOUNTER." (PMID 37109675, 2023). "The TMIGD3 was selected for further analysis, including the single-cell analysis, biological enrichment, tumor microenvironment and immune function analysis." (PMID 37109675, 2023). "Membrane distribution of TMIGD3 protein was observed in the control tumour, whereas in the TMIGD3-knockdown tumour (T6U) the staining intensity was low, thus confirming the specificity of the PAb128 antibody." (PMID 27886186, 2016). "Knockdown of TMIGD3 significantly enhanced primary tumour growth in femurs and metastasis formation in the lungs (SJSA-1) or the livers (Saos2)." (PMID 27886186, 2016). "As TMIGD3 knockdown increased metastasis, we also performed tail vein injection assays to test the ability of tumour cell colonization in the lungs." (PMID 27886186, 2016). "We observed that downregulation of TMIGD3 or A3AR led to increase in tumour growth in SJSA-1 cells." (PMID 27886186, 2016). "Indeed, concomitant knockdown of p65 attenuated sphere formation and subcutaneous tumour growth of SJSA-1 cells enhanced by TMIGD3 knockdown." (PMID 27886186, 2016). "Knockdown of TMIGD3 increases proliferation, tumour formation and metastasis of OS cells." (PMID 27886186, 2016). "To further address the effects of TMIGD3 and A3AR on OS malignancy in vivo, we performed subcutaneous tumour growth assays following knockdown of TMIGD3 or A3AR." (PMID 27886186, 2016). "Hence, restoration of TMIGD3 i1 and A3AR expression levels in tumours is required while using their respective agonists." (PMID 27886186, 2016). "Intriguingly, both TMIGD3 i1 and A3AR inhibit sphere-forming potential, which raises the possibility that they may also regulate stem-like properties of OS including tumour-initiating potential and self-renewability." (PMID 27886186, 2016). "Interestingly, concomitant knockdown of TMIGD3 and A3AR showed a cooperative effect on tumour growth." (PMID 27886186, 2016). "We first validated our generated TMIGD3 antibody (PAb128) for the use of immunohistochemistry (IHC) using SJSA-1-derived tumour tissues with or without TMIGD3 knockdown." (PMID 27886186, 2016). "Similarly, knockdown of A3AR (A2a) in SJSA-1 cells also enhanced tumour growth and lung metastasis in orthotopic injection assays, although metastases were not as robust as TMIGD3 knockdown." (PMID 27886186, 2016). "However, of note, success of clinical trials may rely on the expression levels of TMIGD3 i1 and A3AR in tumours." (PMID 27886186, 2016). "We further performed orthotopic tumour transplantation assays by injecting SJSA-1 and Saos2 cells with or without knockdown of TMIGD3 into the femurs of immunocompromised NOD-scid IL2Rγnull mice." (PMID 27886186, 2016). "Thus, both A3AR and TMIGD3 i1 may not be typical tumour suppressors and rather be tumour modifiers." (PMID 27886186, 2016). "In addition, overexpression of TMIGD3 i1 and A3AR, but not TMIGD3 i3, inhibited migration of SJSA-1 and KHOS/NP cells, as well as tumour growth of SJSA-1 cells, thereby suggesting that TMIGD3 i1 and A3AR suppress malignant properties of OS cells in vitro and in vivo." (PMID 27886186, 2016).
cancer (2 papers, 2016 to 2023). A tumor composed of atypical neoplastic, often pleomorphic cells that invade other tissues. "This is the first report demonstrating the roles of TMIGD3 i1, in the suppression of OS malignancy, as well as NF-κB activity, a commonly deregulated pathway in multiple cancers including OS." (PMID 27886186, 2016). "In addition, future studies to determine expression patters of TMIGD3 i1 in different tissue types and cancers are required for revealing its role in various types of cancer." (PMID 27886186, 2016). "Protein expression of TMIGD3 i1 might also be high in these cancers or could be regulated differently from A3AR." (PMID 27886186, 2016). "Thus, TMIGD3 i1 regulates the PKA−Akt−IκB−NF-κB axis, similar to A3AR, thus reiterating the significance of the GPCR-regulated NF-κB pathway as a potential target for cancer therapy." (PMID 27886186, 2016).
TMIGD3 also shares sentences with these, for which no sentence is quoted: graft versus host disease (1 paper); hepatocellular carcinoma (1); medulloblastoma (1); primary immunodeficiency (1).